IL10 (interleukin 10)
Diseases named in the same sentence as IL10 in open-access papers (continued):
Sharing a sentence is not in itself a finding about the gene and the disease.
tumor (continued). "A previous study showed that distinct subsets of myeloid suppressor cells correlate with plasma IL-6 and IL-10, and impaired response to IFN-α to promote anti-tumour immunity in patients with gastrointestinal malignancies." (PMID 32973748, 2020). "MDSCs suppress anti-tumor immunity through a variety of diverse mechanisms, including ARG1, inducible nitric oxide synthase (iNOS), TGF-β, and IL-10, and PMN-MDSCs and M-MDSCs exhibit different mechanisms of immune suppression." (PMID 32824865, 2020). "Concomitant changes in tumor size, apoptosis markers, tumor killing, and cytokine production in tumors injected with BMM were consistent with in vitro changes in IL-10, IL-12, and other proinflammatory cytokines." (PMID 33036138, 2020). "In another study, the NKG2D ligand RAE-1ε expressed on tumor cells facilitated the expansion and activation of MDSCs that display pronounced ARG1 activity and IL-10 production." (PMID 32793192, 2020). "CRC cells expressing anti-inflammatory cytokines, such as IL-10 and TGF-β, can influence DC phenotype and enhance tumor escape from immune surveillance." (PMID 32235004, 2020). "Matsuda and Sharma observed that Th2 cells-derived IL-10 decreased the MHC-I expression and mediated the inhibition of DC activity, mainly antigen processing and presentation, leading to tumor progression." (PMID 32508847, 2020). "Because IL4, IL13, IL10, and CSF-1 are stimuli in M2 differentiation as reported in previous studies 6, 20, we performed qRT-PCR in FOXO1(+) and FOXO1(-) tumor cells to detect the expression of these genes." (PMID 33052231, 2020). "As described in other studies, we expect alterations in cytotoxic potential, phagocytic capacity or cytokine generation (IL-8, IL-10, MCP-1 and others) for tumor exosome-derived THP-1-M2 macrophages compared to the M0 phenotype." (PMID 32456301, 2020). "In at least one reported study, PRE-084 and (+)-SKF10047 induced the extracellular secretion of IL-10, TGF-β, and PGE2, while decreasing IFN-γ at the tumor site." (PMID 31695608, 2019). "Compared with vaccination using HPV16 long E7 peptide in incomplete Freund’s adjuvant on its own, blocking IL-10 at the time of immunisation elicits significantly higher numbers of CD8+ T cells and attracts more CD4+ and CD8+ T cells to the tumour site." (PMID 31277636, 2019). "Tumor-educated myeloid cells also secrete cytokines TGF-β and IL-10 which, on the one hand, induce expansion of regulatory T lymphocytes (Treg) and, on the other, impact negatively on NK cell and DC activities." (PMID 31555270, 2019). "The majority of the secreted cytokines in MPE are Th2-like and include IL-10, VEGF and TGFβ, further promoting the wound-healing milieu to the detriment of an anti-tumor effector response." (PMID 30999958, 2019). "The increased levels of IL10, VEGF, and EGF in TAMs, in turn, promote treatment resistance by enhancing immune suppression and tumor proliferation." (PMID 31504033, 2019). "Our results indicated that Plasmodium infection significantly inhibits the tumor secretions of GMCSF, IL-10, IL-6, CCL-17, and CCL-22 in vitro through exosomes-like vesicles released by infected red blood cells." (PMID 30979375, 2019). "Therefore, NLGP could be a potential immunotherapeutic drug to inhibit the dialog between tumor stroma and immune cells besides reinforcing its powerful efficacy against IL-10-mediated immunosuppression that ultimately reestablishes the optimum T cell functions of anti-tumor nature." (PMID 31547863, 2019). "Some examples of cytokines that are involved in inflammation and the tumor microenvironment include tumor-necrosis factor-α (TNF-α), interleukin-6 (IL-6), transforming growth factor ß (TGF-β), and interleukin-10 (IL-10)." (PMID 30838040, 2019). "Treg cells coincubated with tumor EVs were shown to upregulate the expression of FasL, TGF-β, IL-10, CTLA4, granzyme B, and perforin and exhibited enhanced suppressor functions." (PMID 31680949, 2019).
tumor (continued). "Knockdown of IL-10RA in ALCL cell lines resulted in growth arrest, implicating aberrantly expressed IL-10 and IL-22 in autocrine loops that provided a mechanism for aberrant TYK2 activation in tumor cells." (PMID 30131584, 2019). "Diverse cytokines and factors, including VEGF, granulocyte-macrophage colony stimulating factor (GM-CSF), IL-6, IL-10, TGF-β, interferon (IFN)-γ, IL-1β, and CCL2, are main attractors of MDSCs toward tumor tissue and affect their activation." (PMID 31484464, 2019). "In fact, tumor angiogenesis contributes to the escape of the immune tumor through the immunosuppressive activity exerted by VEGF, PGE2, IL-10, and tumor hypoxia." (PMID 30991686, 2019). "Among the top 5 degree genes, 2 DEGs (IL10 and XCR1) were highly relative to clinical outcome of ccRCC patients as well as the infiltration of tumor immune cells." (PMID 31781309, 2019). "We observed upregulations of immune checkpoint molecules IL-10, PD1, TGF-β and inflammatory molecule IFN-γ in tumor tissue while SOCS1 and SOCS3 expressions were found to be comparable to controls." (PMID 30859089, 2019). "In the same tumor type, in the presence of oncogenic activated EGFR and KRAS/ERK1/2, EGF promotes the secretion of IL-10 that increases the number of infiltrating Treg cells and M2-polarized TAMs." (PMID 31117237, 2019). "In another study, CHQ has been shown to be an effective anticancer drug in mice by inhibiting tumor resistant MQ (M2 MQ) and decreasing TGF‐β and IL‐10 production." (PMID 29877619, 2019). "Similar to our findings in tumor cell lines, IFN-g preferentially activated STAT1 in Monos, while IL-27 activated both STAT1 and STAT3; IL-10 preferentially activated STAT3." (PMID 31730010, 2019). "Further, IF staining confirmed that acGM-1.8 treatment suppressed the secretion of IL-10 and VEGF-A and stimulated that of IFN-γ in the tumor tissue." (PMID 31118418, 2019). "When the HMDMs were co-treated with resveratrol and tumor-conditioned medium (TCM), the secretion of IL-10, one of the M2-phenotype markers, was significantly lowered in comparison to the group only treated with TCM." (PMID 30791624, 2019). "Monocytes were differentiated and polarized into TAM using tumor-conditioned media (TCM) from breast cancer or lymphoma tumor cells and a cytokine cocktail consisting of IL-4, IL-10, and M-CSF." (PMID 31138333, 2019). "IMQ also reduces Teff production of IL-10 and TGF-beta, thereby reducing tonic inhibitory signals within the tumor." (PMID 30766448, 2019). "Studies have shown that malignant ascites serves as an important tumor microenvironment, which is enriched with tumor-promoting factors such as TGFβ, hepatocyte growth factor (HGF), IL-6, IL-8, IL-10, vascular endothelial growth factor (VEGF) and so on." (PMID 31405096, 2019). "In the COS-treated CRC group (CMCOS), COS protected mice from CRC by decreasing the disease activity index, tumor incidences and multiplicity, and the mRNA levels of COX-2, IL-6, TNF-α, IL-1β, IL-10, and IKK-β mRNA in colonic epithelial cells." (PMID 31620100, 2019). "The model included simulations of M1 release of nitric oxide, M2 release of general tumor growth factors, TEM secretion of angiopoietin-2 and IL-10, and evaluated their effects on tumor progression." (PMID 31075118, 2019). "By contrast, alternatively activated macrophages or M2 macrophages are polarized by anti-inflammatory signals, such as IL10, IL4, and IL13 and are involved in immunosuppression, tumor invasion, tumor growth, angiogenesis and metastasis." (PMID 31096567, 2019). "Similarly, adding cytokines that stimulate the immune system such as IFN-a, IL-2, IL-12, IL-10 and the granulocyte-macrophage colony-stimulating factor (GM-CSF) to the treatment regimen or at high concentrations directly into the tumor microenvironment may also alter immune responses." (PMID 35582566, 2019).
tumor (continued). "We furthermore show that TYK2 is activated by an autocrine loop involving IL-10 and IL-22 and that STAT1 and STAT3 are essential mediators of aberrant tumor cell survival through activation of the pro-survival protein MCL1." (PMID 30131584, 2019). "Tumor tissues from DTT-neoAg-treated mice expressed markedly higher levels of IFN-γ and IL-4 than PBS-treated mice while the levels of IL-12 and IL-10 were similar." (PMID 31749795, 2019). "Hence, blocking IL-10 at the time of treatment with CpG DNA may enhance anti-tumour effects." (PMID 30717461, 2019). "Ablation of CXCR3 in blood cells also reduced the levels of IL-10 and TGF-β in tumors, both of which have been shown to inhibit CRC development by dampening tumor-promoting inflammation." (PMID 31775909, 2019). "They promote tumor growth by iCP expression (CTLA-4, PD-1 and others) as well as production of IL-10 and TGF-β." (PMID 31555274, 2019). "Infiltrated B cells and regulatory T cells (Treg) in TME establish an immunosuppressive environment by the secretion of cytokines such as IL-10 or TGF-β, and hence promote tumor progression." (PMID 30781344, 2019). "Mechanistic analyses revealed that S1P1 promoted BC-associated (i)Treg induction and (n)Treg recruitment in vitro through tumor-derived TGF-β and IL-10 secretion." (PMID 30718502, 2019). "In this study, we have revealed that TRAPs can educate CD4+ T cells to promote tumor growth and metastasis through an HSP90α–TLR2–IL-6–IL-10/IL-21 axis and the induction of IL-10+ Bregs." (PMID 31300052, 2019). "Tumour cells secrete MICA/B, IL-10, TGF-β, and HLA-E to recruit Tregs and inhibit both T cell and NK cell activity." (PMID 30777100, 2019). "Taken together, these results suggest that IL-6, IL-10, and IL-21 from TTRAP augment the differentiation and immunosuppressive function of TRAPs-induced B cells to facilitate tumor growth and metastasis." (PMID 31300052, 2019). "Then, as a result of increased IL-10 and TGF-β levels, their polarization shifts toward a pro-tumor anti-inflammatory phenotype." (PMID 31481956, 2019). "Among the factors for which hampering of the differentiation of DCs is known (IL-10, TGF-β1, VEGF, IL-6, M-CSF, and PGE2), only PGE2 was present in such concentrations in the tumor supernatants to show inhibitory effects on the acquisition of DC morphology." (PMID 31100828, 2019). "Collectively, these findings indicate that targeting IL-10 gene expression with siRNA in DCs before or at the time of immunization can increase vaccine induced CTL responses and block tumour growth in animal models." (PMID 30717461, 2019). "DC-SIGN contributes to the release of IL-10 that would maintain STAT3 activation in tumor cells, thus implying that DC-SIGN favors the maintenance of an activated STAT3 context in the tumor stroma." (PMID 31480382, 2019). "Consistent with previous results, the frequencies of IL-10+ and IL-21+ CD4+ T cells and IL-10+ B cells in tumor-draining lymph nodes and tumor tissues from Il6−/− tumor-bearing mice were significantly decreased." (PMID 31300052, 2019). "Of note, inhibiting autophagy resulted in a significant decrease in the frequency of IL-10+ B cells, IL-21+ and IL-10+CD4+ T cells, as well as a significant increase in IFN-γ+CD4+ T cells, in the tumor-draining lymph nodes and tumor tissue." (PMID 31300052, 2019). "Cytokines, chemokines, and metabolites derived from tumor cells have a significant impact on TME, such as transforming growth factor β (TGF‐β), interleukin (IL)‐10, and CCXL15." (PMID 31365790, 2019). "NK cells exert its function on pathogens, tumor cells, stressed hepatocytes, and HSCs via the production of cytokines (IFN-γ, TNF-α, IL-10, IL-12, IL-22, etc.)and cytotoxic molecules (granzyme B, Perforin, etc.)both in direct or indirect fashion." (PMID 31500589, 2019).
tumor (continued). "Recent studies have demonstrated that tumor-derived Th17 cells produce low levels of TGF-β and IL-10 after stimulation with anti-CD3 in vitro and express CTLA4, FoxP3, and CD25 as Treg cell markers, while they do not suppress tumor progression." (PMID 31024835, 2019). "Tumor-conditioned media (TCM) only, cytokine only (IL-4, IL-10, and M-CSF), TCM with IL-4 and IL-10, TCM with IL-4 and M-CSF, TCM with IL-10 and M-CSF, and TCM with IL-4, IL-10, and M-CSF (the last condition being the in vitro TAM generation method)." (PMID 31138333, 2019). "An anti-IL-10 antibody (JES-2A5) blocked the tumor growth promoting effect of PRE-084, showing that tumor growth is at least partially dependent on IL-10." (PMID 31695608, 2019). "In this respect, we have developed a new vaccination protocol where ex vivo immature DCs were activated with lipid liposomes formulated with tumour antigens and an IL-10 siRNA capable of co-coordinately activating DCs via TLR7/8 and silencing IL-10 expression." (PMID 30717461, 2019). "MDSCs use vast inflammatory mediators to suppress anti-tumor immunity, e.g., arginase 1 (ARG1), transforming growth factor β (TGF-β), interleukin 10 (IL-10), and indoleamine 2,3-dioxygenase (IDO)." (PMID 31001284, 2019). "Recombinant human IL-10 induced the expression of IFN-γ and granzymes in tumor-bearing mice through CD8‏+ T-cell–dependent manner." (PMID 31653148, 2019). "TAMs isolated from RCC produce large amounts of immunosuppressive interleukin-10 (IL-10) and CCL-2, which attracts monocytes to the tumor site." (PMID 31259150, 2019). "Tumor-resident CD8+ T-cells express high levels of IL-10R, leading to high levels of activated pSTAT3 and pSTAT1 in response to IL-10." (PMID 31480382, 2019). "In this respect, it is worthy noting that in our study IL-10 alone was insufficient to upregulate TIM-3 expression, suggesting that multiple components of the tumor microenvironment are needed for taming DCs with TIM-3." (PMID 31244860, 2019). "Based on the effect of YFTL on splenic lymphocytes and NK cell, the cytokine levels of IL-2, IFN-γ, IL-10, and TGF-β1 in the serum of tumor-bearing mice were detected." (PMID 30781674, 2019). "CD19+ Tim‐1+ cells down‐regulated the function of effector CD4+CD25low T cells ex vivo dependent on IL‐10 production, and adoptive transfer of CD19+ Tim‐1+ cells promoted tumour growth in mice." (PMID 30467955, 2019). "Taken together, caerin peptides are able to boost the efficacy of a HPV16 E7 peptide-based vaccine containing IL-10 signalling inhibitor to better inhibit the HPV16 E6/E7 transformed TC-1 growth and extend the survival time of TC-1 tumour bearing mice." (PMID 31277636, 2019). "In the mice bearing knock-down B16F10 tumors, the frequency of IL-21+ and IL-10+ CD4+ T cells in the tumor draining lymph node and tumor tissue and the serum IL-6 level were significantly reduced as compared to those in the mice bearing control tumors." (PMID 31300052, 2019). "Soluble factors that are abundant in K-ras mutant LUAD, such as MDSC-, macrophage- and tumor cell-derived TGF-β, PGE2, IDO, and IL-10, also inhibit NK cell function." (PMID 32039025, 2019). "Hypoxia upregulates some inhibitory signals for anti-tumor immune response such as PD-L1, indoleamine 2, 3-dioxygenase (IDO), interleukin-6 (IL-6), and interleukin-10 (IL-10)." (PMID 30925919, 2019). "These cells are recruited in response to IL-6, IL-10 and TGF-β secretion by the tumor cells to downregulate tumor antigen recognition, prevent T cell proliferation and inhibit cytotoxic T cell function." (PMID 35582566, 2019). "The concentrations of IL-6, IL-10, and TGF-β significantly increased in the ascites during tumor progression, as we showed in a previous study." (PMID 31753019, 2019).
tumor (continued). "Many cancers can produce or induce the immune cells in tumor stroma to produce an array of immunosuppressive cytokines including transforming growth factor (TGF‐β) and IL-10, which inhibit the recruitment and activation of antitumor T lymphocytes." (PMID 30046565, 2018). "Indeed, VEGF may attract immature myeloid cells from the BM into the tumor where, in cooperation with other factors, such as IL-10 and TGF-β, induces these precursors to differentiate into M2 macrophages or may also directly recruit macrophages to the tumor site." (PMID 30154786, 2018). "We have shown that several cytokines/chemokines, important for immune activation were upregulated after nivolumab treatment in which one important cytokine (IL-10) and chemokine (CX3CL1/Fractalkine) were significantly reduced at tumor progression." (PMID 30108590, 2018). "In summary, our results suggested that AML cells expressed ICOSL promote the expansion of ICOS+ Tregs in tumor environment, and ICOS+ Tregs further promote the proliferation of AML cells through secreting IL-10." (PMID 30319662, 2018). "Elevated concentrations of IL-10 in the sera of children with ALK-positive ALCL before treatment correlated with the presence and quantity of circulating tumor cells." (PMID 29642597, 2018). "The release of interleukin IL-12 and IL-6 was enhanced by TLY-DCs at a ratio of 1 DC: 3 tumor apoptotic bodies (APO), however, the release of IL-10 was suppressed." (PMID 30081891, 2018). "Raw data from tumor volume and weight, ELISA (PGE2, IL-10 and VEGF) and morphometric quantification (VEGF, VEGFR-2, MMP-9 and COX-2)." (PMID 29609579, 2018). "The tumor-bearing mice in the model group had higher levels of TGF-β1 and IL-10 in serum than those in the control group (P < 0.01), while LBP-treated mice had lower levels of such cytokines in serum when compared with model mice (P < 0.05 and P < 0.01, resp)." (PMID 29967800, 2018). "They promote tumor growth by diverse mechanisms, including expression of immune checkpoints (CTLA-4, PD-1 and others) as well as production of IL10 and transforming growth factor-beta (TGF-β)." (PMID 29970158, 2018). "We have previously shown that elderly derived macrophages display a heightened response to tumor-derived factors, leading to increased production of TGF-β and IL-10." (PMID 30459812, 2018). "Macrophages play an important role in tumor growth and progression as they produce a large quantity of cytokines such as tumor necrosis factor-α (TNF-α), interleukin-10 (IL-10), and interferon-γ (IFN-γ)." (PMID 29361917, 2018). "Tregs located in the tumor microenvironment mediate immunosuppression by releasing cytokines such as TGF-β and IL-10." (PMID 29032503, 2018). "GBM plays role in generating immunosuppressive microenvironment by producing different immunosuppressive cytokines including IL-6, IL-10, and TGF-β as well as tumor aggravating IL-1 and basic fibroblast growth factor (bEGF) resulting in neuroinflammation." (PMID 29651429, 2018). "For instance, tumours can instruct intratumoral macrophages to overexpress and secrete Gas6 by producing IL-10 and M-CSF in the microenvironment, and Gas6 binds to TAM receptors in tumour cells and immune cells, promoting tumour progression." (PMID 29386018, 2018). "Overexpression of immunosuppressive cytokines, such as IL-10, TGF-β and IL-1β can cultivate a Tumor Microenvironment (TME) conducive to evasion and tumor proliferation." (PMID 29988281, 2018). "Recently, it has been suggested that tumor-infiltrated B cells develop immunosuppressive properties via enhanced expression of TGF-β, PD-L1, CD86, and IL-10." (PMID 29599908, 2018). "In relation to the increase in T cells, our results confirmed the induction of genes as Cd3g, Cd4, Il6, Il10 and Il12a in spleens of Ats1-KO mice, independently of the absence or presence of B16F1 tumours." (PMID 30166561, 2018). "Such lymphocytes can be produced in tumor tissue thanks to the cytokines produced by tumor cells as GCS-F and IL-10." (PMID 30155493, 2018).